PTPRR (protein tyrosine phosphatase receptor type R)
Description:
Sequesters mitogen-activated protein kinases (MAPKs) such as MAPK1, MAPK3 and MAPK14 in the cytoplasm in an inactive form. The MAPKs bind to a dephosphorylated kinase interacting motif, phosphorylation of which by the protein kinase A complex releases the MAPKs for activation and translocation into the nucleus (By similarity).
Synonyms: PTPRQ; PTPBR7; PTP-SL; EC-PTP; PCPTP1
Tractability: Antibody: UniProt places it where antibodies can reach, with high confidence; its Gene Ontology location is reachable by antibodies, with high confidence; UniProt predicts a signal peptide or a membrane-spanning region; the Human Protein Atlas places it where antibodies can reach. PROTAC: its protein half-life has been measured.
Target class: Enzyme; Protein Phosphatase; Receptor tyrosine-protein phosphatase; Tyrosine protein phosphatase; Phosphatase
Gene: Protein-coding gene on chromosome 12 (70,638,073 to 70,920,738, reverse strand). Ensembl gene ENSG00000153233.
Subcellular location: Secreted; Cell membrane (Isoform Alpha); Cytoplasm, perinuclear region (Isoform Delta); Cytoplasm, perinuclear region (Isoform Gamma)
Subcellular location (Human Protein Atlas): Cell Junctions; Cytosol; Plasma membrane; Predicted to be secreted
Gene Ontology:
Molecular function: protein binding; protein kinase binding; protein tyrosine phosphatase activity; transmembrane receptor protein tyrosine phosphatase activity
Biological process: ERBB2 signaling pathway; in utero embryonic development; negative regulation of epithelial cell migration; negative regulation of ERK1 and ERK2 cascade; regulation of homophilic cell adhesion; protein dephosphorylation; signal transduction
Cellular component: cell junction; cytosol; extracellular region; plasma membrane; perinuclear region of cytoplasm
Genetic constraint (gnomAD): Loss-of-function variants: 29 observed, 62.5 expected, observed/expected ratio (o/e) 0.46, 90% interval 0.34 to 0.63. The upper end of that interval is the gene's LOEUF score, 0.63, which puts it in group 2 of 6, group 1 being the genes least tolerant of losing a copy. Missense variants: 655 observed, 734.02 expected, observed/expected ratio (o/e) 0.89, 90% interval 0.84 to 0.95. Synonymous variants: 261 observed, 263.4 expected, observed/expected ratio (o/e) 0.99, 90% interval 0.89 to 1.1.
Homologues: Orthologues: chimpanzee PTPRR (99% identical), macaque PTPRR (98% identical), guinea pig PTPRR (93% identical), dog PTPRR (92% identical), pig PTPRR (91% identical), rabbit PTPRR (91% identical), mouse Ptprr (89% identical), rat Ptprr (89% identical), tropical clawed frog ptprr (74% identical), zebrafish ptprr (40% identical). Paralogues in human: PTPN5 (35% identical), PTPN7 (29% identical), PTPRB (24% identical), PTPRJ (22% identical), PTPRF (22% identical), PTPRS (21% identical), PTPRH (21% identical), PTPN13 (21% identical), PTPRD (20% identical), PTPRT (20% identical), PTPRK (20% identical), PTPRO (20% identical), and 23 more.
Diseases named in the same sentence as PTPRR in open-access papers:
PTPRR is named in the same sentence as 37 diseases in open-access papers, as found by Europe PMC text mining. Sharing a sentence is not in itself a finding about the gene and the disease. The quoted sentences say what the papers report.
cervical cancer (10 papers, 2014 to 2023). A primary or metastatic malignant neoplasm involving the cervix. "PTPRR is usually methylated in cervical cancer and as a MAP kinase pathway inhibitor, impacts various aspects." (PMID 31766427, 2019). "PTPRR is a subfamily of classical PTPs and is considered as a tumor suppressor regulating proliferation or differentiation of cancer cells including oral squamous cell carcinoma, cervical cancer, breast tumor, and colorectal carcinomas." (PMID 36105254, 2022). "Cervical cancer cells carry aberrantly high methylation rates of PTPRR." (PMID 31366565, 2019). "Promoter methylation of PTPRR was found in invasive cervical cancer cell lines and tissues." (PMID 29029430, 2017). "Repression of PTPRR expression via methylation has been detected in pre-cancerous colorectal lesions and in cervical adenocarcinoma, and in cervical cancer PTPRR may have a role in metastasis and be a biomarker of invasive cervical cancer." (PMID 25592066, 2015). "Epigenetic silencing of PTPRR resulting from DNMT3B-mediated methylation activates MAPK signaling, promotes metastasis and serves as a biomarker of invasive cervical cancer." (PMID 37965307, 2023). "A previous study demonstrated that the PTPRR gene exerts an inhibitory effect on p44/42 MAPK signaling and transcription factor AP1 expression in cervical cancer." (PMID 24270600, 2014).
colorectal cancer (6 papers, 2009 to 2025). A primary or metastatic malignant neoplasm that affects the colon or rectum. "Here, we show that levels of both major PTPRR transcript variants are markedly decreased (compared with normal mucosal levels) in precancerous and cancerous colorectal tumors, as well in colorectal cancer cell lines." (PMID 20015382, 2009). "In the present study, we used real-time quantitative RT-PCR with specific primers to assess the levels of PTPRR transcript variants 1 and 2 (PTPRR-1 and PTPRR-2) in snap-frozen samples of colorectal tumors (precancerous and cancerous) and in colorectal cancer cell lines." (PMID 20015382, 2009). "And, PTPRR functions as a tumor suppressor in ovarian cancer by dephosphorylating and inactivating β-catenin, and in colorectal cancer via inhibiting the Ras/ERK/c-Fos signaling pathway." (PMID 37965307, 2023). "The same study also revealed dramatically reduced PTPRR transcript levels in 25 colorectal cancers and 18 colorectal cancer cell lines, suggesting that PTPRR downregulation is an early but persistent alteration in colorectal carcinogenesis." (PMID 20015382, 2009).
ovarian carcinoma (5 papers, 2021 to 2024). A malignant neoplasm originating from the surface ovarian epithelium. "PTPRR downregulation is reported in ovarian cancer; its re-expression reduces cell proliferation, inhibiting tumorigenesis." (PMID 38612874, 2024). "While far less is known about ARID3C, RNA-Seq analyses recently identified it within a signaling complex consisting of protein tyrosine phosphatase receptor type R (PTPRR), α-catenin, β-catenin, and E-cadherin that form exclusively in ovarian cancer." (PMID 33804610, 2021).
colon cancer (3 papers, 2009 to 2024). "In some cancers, such as breast and colon cancer, overexpression of a protein that silences PTPRR leads to activation of MAPK signalling and epithelial-mesenchymal transition (EMT)." (PMID 37958407, 2023).
bladder cancer (2 papers, 2024). "However, there is limited research on the relevance of PTPRR in bladder cancer, which warrants further investigation in the future." (PMID 38341586, 2024).
myopia (2 papers, 2021 to 2022). "Genetic studies on high-grade myopia indeed pointed to a strong association with a missense mutation (rs3803036) in PTPRR and meta-analyses of PTPRR variant rs11178469 also revealed a relationship with visual refractive errors." (PMID 36755664, 2022). "In a Caucasian family cohort study, PTPRR rs3803036 was found to be strongly associated with high myopia." (PMID 34122509, 2021). "Explorations with large cohorts should be conducted in different ethnic groups to further evaluate the role of PTPRR and the impacts of PTPRR on myopia risk factors." (PMID 34122509, 2021). "Expansion of data and inclusion of additional ethnic groups may clarify this putative contribution of PTPRR to myopia risk factors." (PMID 36755664, 2022). "We also evaluated the roles of RASGRF1 rs6495367, PDGFRA rs6554163, and PTPRR rs11178469 in myopia in a southern Chinese Han population." (PMID 34122509, 2021).
oral squamous cell carcinoma (2 papers, 2015 to 2022). "PTPRR expression has also recently been identified as a prognostic indicator in oral squamous cell carcinoma." (PMID 25592066, 2015).
pancreatic cancer (2 papers, 2017 to 2026). "We also identified novel pancreatic cancer genes, such as SCML2, COL17A1, AMIGO2, PTPRR, suggesting our method might be able to predict novel PDAC-related genes." (PMID 28611293, 2017).
prostate carcinoma (2 papers, 2015 to 2017). A carcinoma that arises from epithelial cells of the prostate gland. "We examined PTPRR gene expression in prostate cancer clinical samples using previously published datasets that are publically available." (PMID 25592066, 2015). "In summary, our study has identified the protein tyrosine phosphatase PTPRR as an early and direct target of the androgen receptor that is rapidly repressed by androgens in prostate cancer cells." (PMID 25592066, 2015). "Comparison of PTPRR expression by Affymetrix Array of 14 samples reported a 3.381 fold reduction in prostate cancer relative to normal tissue, and a 4.686 fold reduction in metastatic versus primary prostate cancer." (PMID 25592066, 2015). "While PTPRR is a member of the protein tyrosine phosphatase (PTP) family, which is known to be related with prostate cancer, KRT15 is a member of the keratin gene family, which is known to be associated with breast cancer and lung cancer." (PMID 29100492, 2017). "We also demonstrate that over-expression of PTPRR in androgen stimulated cells is sufficient to decrease phosphorylation of ERK1/2 and reduce both the expression of oncogenic transcription factors and proliferation of prostate cancer cells." (PMID 25592066, 2015).
Alzheimer disease (1 paper, 2009). A progressive, neurodegenerative disease characterized by loss of function and death of nerve cells in several areas of the brain leading to loss of cognitive function such as memory and language. "PTPRR is a human homologue of PTP-SL and there are reports indicating its involvement in nerve growth factor signaling, thus representing potential target in the therapy of neurodegenerative processes, like Alzheimer disease." (PMID 19424502, 2009).
colorectal adenoma (1 paper, 2009). An adenoma that arises from the colon or rectum. "In our recent analysis of the transcriptomes of 32 colorectal adenomas, PTPRR emerged as one of the most markedly downregulated genes in these precancerous tissues." (PMID 20015382, 2009).
colorectal tumors (1 paper, 2009). "Better understanding of the functional effects of PTPRR loss could shed light on important aspects of the mechanisms underlying colorectal tumor cell survival, in particular on the dynamics of constitutive activation of the RAS/RAF/MAPK/ERK signaling." (PMID 20015382, 2009). "However, in addition to being detected in the vast majority of the precancerous lesions we examined, it was also present in almost all of the more advanced colorectal tumors, suggesting that downregulated PTPRR expression is also associated with clonal expansion." (PMID 20015382, 2009).
diabetes type II (1 paper, 2018). "Additionally, we found a considerable number of genes with links to the MAPK signaling cascade, e.g. MAPK1 and PTPRR, involved in glucose and lipid metabolism, or putatively responsible for insulin resistance or diabetes type II or obesity." (PMID 30231878, 2018).
epilepsy (1 paper, 2022). A brain disorder characterized by episodes of abnormally increased neuronal discharge resulting in transient episodes of sensory or motor neurological dysfunction, or psychic dysfunction. "Since ERK activation causes seizures and epilepsy, it seemed interesting to investigate PTPRR regulation during epileptogenesis." (PMID 35163126, 2022).
lymph node metastasis (1 paper, 2026). "High PTPRR expression correlated with lymph node metastasis, advanced stage, and poor prognosis (Log-rank P<0.05), serving as an independent adverse prognostic factor." (PMID 42212130, 2026).
neuroblastoma (1 paper, 2021). Neuroblastoma (NB) is the most common solid, extracranial childhood tumor. "Interestingly, a distinct pattern of PTPRR, PTPN5, and PTPN7 mRNA expression was observed in human neuroblastoma cell lines upon retinoic acid differentiation, with down-regulation of PTPN5 and up-regulation of PTPN7 and, to a lesser extent, PTPRR." (PMID 34957126, 2021).
prostate tumours (1 paper, 2015). "Although this was a small sample set, the data suggested PTPRR has a heterogeneous expression profile in prostate tumour clinical samples." (PMID 25592066, 2015).
rectal cancer (1 paper, 2024). A primary or metastatic malignant neoplasm that affects the rectum. "Suppression of PTPRR expression in rectal cancer triggers the Ras/ERK/c-Fos signaling pathway, thereby facilitating the development of rectal carcinogenesis." (PMID 38714855, 2024).
cancer (15 papers, 2009 to 2026). A tumor composed of atypical neoplastic, often pleomorphic cells that invade other tissues. "Ascore comprises four genes (CERCAM, EMP1, GNLY, and PTPRR), which have been previously reported to be strongly associated with cancer." (PMID 38341586, 2024). "We analyzed the clinical outcomes associated with miR-218-5p and PTPRR using another database from TCGA and found significant differences between miR-218-5p and PTPRR in both cancer mucosa and adjacent normal tissues of pan-cancer." (PMID 36627634, 2023). "Studies suggest that PTPRR negatively regulates cell proliferation in cancer cells, prompting an intriguing evaluation of its potential role in the Hippo pathway in tumorigenesis." (PMID 38612874, 2024). "There are likely additional mechanisms that can lead to decreased levels of CGN and PTPRR because not all cancers show increased expression of miR-100 or miR-125b, but the data are in agreement that decreased levels of CGN and PTPRR correlate with cancer." (PMID 39697634, 2024). "Regarding CRC data, the differences in the abundance of miR-218-5p and PTPRR in both cancer tissues and adjacent normal tissues were consistent with our data." (PMID 36627634, 2023). "Dysregulation of PTPRR and MKP are implicated in the development and progression of various cancers owing to their ability to regulate both p38 and JNK MAPK pathways." (PMID 34187521, 2021). "PTPRR has been identified as a physiologic regulator of ERK signaling in several cancer types." (PMID 41808249, 2026). "Moreover, high expression of PTPRR, which is involved in this pathway, has been described in several types of cancer." (PMID 38674117, 2024). "The analysis of heatmaps revealed that PDGFRA and PTPRR demonstrated high SNV across various cancers, whereas PTPRR and RAC3 exhibited elevated CNV in the majority of cancer types." (PMID 38714855, 2024). "We used the GENT2 database to compare the levels of CGN and PTPRR between normal and cancer tissues and found that CGN is downregulated in 19/35 cancers including CRC (red brackets) while PTPRR is downregulated in 16/35 including CRC." (PMID 39697634, 2024). "We thus sought to test if decreased expression of CGN and PTPRR due to increased expression of miR-100 and miR-125b might be observed in CRC and other cancers." (PMID 39697634, 2024).
tumor (14 papers, 2009 to 2026). "Although PTPRR is only mutated in 1% of PCa tumours, our data demonstrates that it is a key component of the clinically important RAS/ERK1/2 signalling pathway, and that its expression level can have a clear affect on the activity of this pathway." (PMID 25592066, 2015). "Epigenetic downregulation of PTPRR seems to be an early alteration in colorectal cell transformation, which is maintained during the clonal selection associated with tumor progression." (PMID 20015382, 2009). "Our analysis of a large series of human tumors and cell lines indicates that epigenetic downregulation of PTPRR occurs early in colorectal cell transformation and is maintained during the clonal selection associated with tumor progression." (PMID 20015382, 2009). "Furthermore, low PTPRR expression in tumor specimens was associated with shorter progression-free and overall survival for patients with NSCLC treated with sotorasib." (PMID 41808249, 2026). "The protein encoded by PTPRR belongs to the protein tyrosine phosphatase (PTP) family, which exhibits tumor suppressive properties." (PMID 38341586, 2024). "Compared to normal tissues, tumor tissues displayed a significant increase in staining intensity for PTPRR and RAC3." (PMID 38714855, 2024). "IHC detection of ERK1/2, c-Fos, and PTPRR was performed on the tumor tissues of the two xenograft model experiments." (PMID 36627634, 2023). "On the counterpart, 40435_at (SLC25A6), 33614_at (RPL18A, RPL18AP3), and 1657_at (PTPRR) are down-regulated (high expression values in normal class and low expression values in tumor class)." (PMID 33375940, 2020). "PTEN expression was also detected in 5/6 of these clinical PCa samples, but one tumour (sample 3) had low levels of both PTPRR and PTEN." (PMID 25592066, 2015). "PTPRR silencing may thus represent a novel mechanism by which neoplastic colorectal cells evade tumor suppression." (PMID 20015382, 2009). "Differential expression analysis of 10 genes in tumor and normal tissues showed that RAC3 and PTPRR were highly expressed in tumor tissues, while the rest of the genes were lowly expressed in tumors (p < 0.05)." (PMID 38714855, 2024).
psychiatric disorder (1 paper, 2009). A disorder characterized by behavioral and/or psychological abnormalities, often accompanied by physical symptoms. "Future studies should also examine possible links between loss or reduced expression of PTPRR in the nervous system and neurological and psychiatric disorders." (PMID 20015382, 2009).
PTPRR also shares sentences with these, for which no sentence is quoted: asthma (2 papers); Lung Fibrosis (2); Ataxia (1); breast carcinoma (1); breast tumor (1); cervical adenocarcinoma (1); glioblastoma (1); infection (1); inflammation (1); Insulin resistance (1); lung carcinoma (1); major depressive disorder (1); melanoma (1); Obesity (1); psoriasis (1); sarcoidosis (1).